SOX9 (SRY-box transcription factor 9)
Diseases named in the same sentence as SOX9 in open-access papers (continued):
Sharing a sentence is not in itself a finding about the gene and the disease.
glioma (continued). "All these results suggested that SOX9 was a direct target of miR-101 in glioma." (PMID 27911279, 2017). "Simultaneously, SOX9 was proved to be essential for glioma progression." (PMID 27911279, 2017). "Taken together, our findings suggest that miR-101 regulates glioma proliferation, migration and invasion via directly down-regulating SOX9 both in vitro and in vivo, and miR-101 may be a potential therapeutic target for future glioma treatment." (PMID 27911279, 2017). "However, the role of SOX9 in promoting glioma stemness and progression has been widely reported." (PMID 40374599, 2025). "Additionally, analysis of proteomics data from the Clinical Proteomic Tumour Analysis Consortium (CPTAC) confirmed that SOX9 protein expression in glioma tissue is significantly higher than that in normal brain tissue, and this pattern is consistent with the changes observed for USP18 expression." (PMID 40374599, 2025). "Thus, Sox9 is a predictive biomarker for the pathogenesis and prognosis of clinical glioma." (PMID 33613515, 2020). "Thus, Sox9 plays an essential role in maintenance of the malignant phenotypes of glioma cells." (PMID 33613515, 2020). "Moreover, experiments in vitro revealed that their levels, especially of SOX1 and SOX2, were significantly elevated in PR-LncRNA silencing cells and that knock-down of SOX1 and SOX9 expression dramatically reduced the pro-oncogenic activities promoted by PR-LncRNA silencing in glioma cells." (PMID 30143669, 2018). "Therefore, we investigated the relationship between SOX9 and miR-101 in glioma in this study." (PMID 27911279, 2017). "To present, no studies have evaluated that whether genetic variants of SOX9 contribute to susceptibility of gliomas." (PMID 27589569, 2016). "Increasing evidence indicates that aberrant activation of the SOX9 signalling pathway contributes to the acquisition of CSC characteristics in cancer types, including glioma." (PMID 40374599, 2025). "In the TCGA glioma dataset, SOX9 expression was found to be significantly positively correlated with several GSC markers, further emphasising its role in glioma stemness." (PMID 40374599, 2025). "Another study also showed that circPTN promotes glioma growth and stemness by sponging miR-145-5p and miR-330-5p, this results in increased expression of NES, CD133, SOX9 and SOX2, which promotes self-renewal of glioma stem cells and regulates gliomagenesis." (PMID 39698112, 2024). "SOX9, a player in CSC sustenance, is also responsible for cell senescence in gliomas and works synergistically with SOX2." (PMID 36834653, 2023). "We analyzed SOX9, STAT3/p-STAT3, and PML expression in a set of established glioma cell lines and patient-derived cells cultures by immunoblot." (PMID 35562901, 2022). "HDAC6 was also enriched in glioma stem cells,and its expression positively correlated with several GSC markers(SOX2, SOX9, CD133, NESTIN, and OCT4)." (PMID 35786935, 2022). "The presence of astrocyte-like SOX9+ and oligodendrocyte-like OLIG1+ cells in grade II IDH1-mutant gliomas raises new questions about their role in the pathology." (PMID 33925547, 2021). "Here we confirmed high expression of lncRNA-ANRIL and SOX9 in glioma and proved that the inhibition of lncRNA-ANRIL and SOX9 can modulate the multiplication, invasion, and apoptosis of glioma cells." (PMID 34556140, 2021). "The 3-year survival was markedly higher in the high-lncRNA-ANRIL group and high SOX9 group than in the low-lncRNA-ANRIL group and low SOX9 group, suggesting that lncRNA-ANRIL and SOX9 are related to the prognosis of patients with glioma." (PMID 34556140, 2021). "The area under the ROC curve (AUC) for glioma diagnosis was 0.860 for lncRNA-ANRIL and 0.857 for SOX9." (PMID 34556140, 2021). "Consistently, data from Chinese Glioma Genome Atlas (CGGA) and the Cancer Genome Atlas (TCGA) suggested that high Sox9 expression correlates with short survival of glioma patients." (PMID 33613515, 2020).
glioma (continued). "Treatment of glioma cells with cycloheximide (CHX), which prevents translocation of elongating ribosomes, revealed that TGF-β pathway protected Sox9 protein from the degradation." (PMID 33613515, 2020). "Our data showed that SOX9 and PDK1 exhibited the similar function in glioma colony formation and sphere formation." (PMID 29416606, 2018). "Similar results have been reported that rapamycin decreased glioma stem cell activity and temozolomide resistance through SOX2/SOX9 expression." (PMID 28903328, 2017). "Notably, SOX9 and USP18 protein levels exhibited a statistically significant positive correlation in glioma tissues." (PMID 40374599, 2025). "It has already been found that the high proliferation and invasion of gliomas and the poor prognosis in glioma patients are usually accompanied by SMAD signaling in early studies, and Sox9 becomes an important regulatory target when TGF-β works in glioma progression." (PMID 35461253, 2022). "Sox9 functions downstream of the transforming growth factor-β (TGF-β) pathway, in which TGF-β signaling prevent proteasomal degradation of the Sox9 protein in glioma cells." (PMID 33613515, 2020). "Various studies have found that Sox9 represents a negative prognostic factor in different types of cancer, including glioma and lung." (PMID 30622340, 2019). "Of note, although SOX9 hypermethylation in IDH mutant gliomas has been reported in several studies, we did not detect significant methylation in either primary tissue sample or xenograft." (PMID 24077805, 2013). "Furthermore, we performed Kaplan‒Meier survival analysis on glioma patient datasets from TCGA and CGGA, which revealed that high SOX9 expression is correlated with poor clinical outcomes across multiple glioma cohorts (CGGA693-primary glioma, CGGA693-recurrent glioma, TCGA-LGG, and TCGA-GBM)." (PMID 40374599, 2025). "Quantitative reverse transcription PCR and Western blotting analysis revealed a negative relationship between miR-101 and SOX9 in human glioma U251MG and U87MG cells, and the luciferase assay indicated that miR-101 altered SOX9 expression by directly targeting on 3′UTR." (PMID 27911279, 2017).
colon carcinoma (53 papers, 2008 to 2025). "Activation of the stemness factor SOX2 in Sox9-defective colon cancers is linked to EMT induction and an enhanced metastatic phenotype." (PMID 40179020, 2025). "In colon cancer cells, SOX9 was predicted to modify splicing patterns by its association with Y14, an RNA-binding protein that forms part of the exon junction complex." (PMID 38238288, 2024). "Taken together, DKK2-driven loss of HNF4α1 protein enhances Sox9 expression in colon cancer cells to generate LYZ+ cells with Paneth cell properties." (PMID 38659853, 2024). "Sox9 overexpression was found in human cancers including prostate, lung and colon cancers, and is associated with more aggressive clinicopathological features and poorer prognosis." (PMID 27105493, 2016). "The clinical sample results expanded our findings in model systems showing that SOX9 and S100P are co-expressed and associated with metastasis and invasion, thereby influencing prognosis in colon cancer." (PMID 26009899, 2015). "Expression of SOX9 and S100P is strongly correlated in primary colon cancer tissues and is associated with adverse prognosis." (PMID 26009899, 2015). "Notably, DKK2 induces the loss of HNF4α1 isoform in colon cancer cells followed by elevation of Sox9 expression lead to the formation of LYZ+ cancer cells exhibiting Paneth cell properties." (PMID 38659853, 2024). "The expression of MiniSOX9, a SOX9 splice variant that behaves as a dominant negative inhibitor of SOX9 together with the presence of inactivating mutations of SOX9 might account for the weak transcriptional activity of SOX9 in colon tumor cells." (PMID 27429045, 2016). "Together, these findings led us to hypothesize that SOX9 may directly or indirectly regulate S100P and may be associated with aggressive phenotypes of colon cancer." (PMID 26009899, 2015). "We previously identified Hsa_circ_0020095 as a novel oncogene to promote progression and cisplatin-resistance in colon cancers by modulating the miR-487a-3p/SOX9 axis." (PMID 40495972, 2025). "In our previous work, we have identified hsa_circ_0020095 as a novel oncogene to promote progression and cisplatin-resistance in colon cancers by modulating the miR-487a-3p/SOX9 axis." (PMID 40495972, 2025). "To further evaluate the role of SOX9 in human CRCs, we examined SOX9 protein expression by IHC in relation to clinicopathological factors using a human colon tumor primary tissue microarray (TMA)." (PMID 40179020, 2025). "Compared with effects of Apc inactivation in mouse colon tumors, combined Apc and Sox9 inactivation instigated more invasive tumors with epithelial-mesenchymal transition (EMT) and SOX2 stem cell factor upregulation." (PMID 40179020, 2025). "We confirmed strong nuclear expression of the SOX2 protein in S and AS mouse primary colon tumors and organoids where the Sox9 gene is inactive, whereas only approximately 5% of cells in tissues from A mice showed weakly positive SOX2 staining." (PMID 40179020, 2025). "Here we showed that DKK2-mediated HNF4α1 protein degradation enhanced Sox9 expression in colon cancer." (PMID 38659853, 2024). "This analysis revealed that higher expression levels of CTNNB1 and SOX9 were correlated with low numbers of γδ T cells in human colon cancer." (PMID 37309673, 2023). "Colon cancer cell progression and cisplatin resistance can be accelerated by circ_0020095/miR-487a-3p/SOX9 axis." (PMID 36539702, 2022). "The IHC score for SOX9 in the normal and cancer cells of the colon cancer tissue in the CC group was higher than that in the normal cells of the control group." (PMID 33807620, 2021). "Carrasco-Garcia found that the overexpression of SOX9 was associated with metastatic status and enhanced self-renewal ability in colon cancer cells through their in vivo study, while the colon tumorigenesis was declined in SOX9 knockdown mice." (PMID 35201494, 2021).
colon carcinoma (continued). "Using loss of function mouse models, human colon cancer cells, and tumor microarray data sets we evaluated the role of RIP140 in SOX9 expression and activity using RT-qPCR, immunohistochemistry, luciferase reporter assays, and GST-pull down." (PMID 34206767, 2021). "Nevertheless, SOX9 has also been found to be overexpressed in some CRCs, and oncogenic functions have been reported for SOX9 in the context of colon tumour development." (PMID 32961708, 2020). "Other studies showed that an increased MALAT1 expression promotes the proliferation of colon cancer cells, although by regulating other targets such as SOX9 and miR-129-5p/HMGB1 axis." (PMID 31733641, 2020). "Knockdown of SOX9 expression results in reduced invasiveness and metastasis of colon cancer cells and inhibits the tumor growth and peritoneal metastasis in nude mice by inhibiting the S100P/RAGE/ERK/EMT signaling pathway." (PMID 33520987, 2020). "SOX9, S100P transcription factor, increased S100P expression promote metastasis and invasion and result in low survival in colon cancer patients." (PMID 33117687, 2020). "Conversely, low levels of SOX9 at the invasive front of the primary tumor have been shown as an independent predictor of relapse in stage II colon cancer patients." (PMID 31057614, 2019). "Treatment with the synthetic PPARγ ligand rosiglitazone induced different changes of SOX9 and β-catenin expression and subcellular localization in the colon cancer cell lines Caco2, SW480, HCT116, and HT29." (PMID 31057614, 2019). "In esophageal cancer, Sox9 promotes tumorsphere formation and invasive capacity; and in colon cancer it enhances tumorigenicity." (PMID 27105493, 2016). "Nevertheless, it has to be taken into account that SOX9 transcriptional activity is low in intestinal tumor cell lines and this might be due, at least partly, to inactivating mutations of the SOX9 gene, but also to our discovery of MiniSOX9 in colon cancer cells." (PMID 27429045, 2016). "Pygo2 failed to suppress Sox9 overexpression in Apc LOF, and only partially reduced elevated Sox9 in colon tumors and Ctnnb1 GOF mice." (PMID 27811361, 2016). "On signaling pathways, Sox9 binds directly to BMI1 in colon cancer, co-operates with slug to induce mammary stem cells in the breast, and drives tumorigenesis through the ERBB pathway in the pancreas." (PMID 27105493, 2016). "As a transcription factor of S100P, SOX9 binds to and activates S100P promoter, and induces invasiveness and metastasis of colon cancer cells." (PMID 26755651, 2016). "Sox9, a target of Wnt signaling expressed in Paneth cells, was shown to be overexpressed in several human malignancies including colon cancer." (PMID 27811361, 2016). "Inversely, low levels of SOX9 at the invasive front of the primary tumor have even been shown to be an independent predictor of relapse in stage II colon cancer patients." (PMID 27429045, 2016). "Knockdown of SOX9 expression decreased S100P expression, resulting in the reduced invasiveness and metastasis of colon cancer cells by inhibiting EMT shift." (PMID 26755651, 2016). "By constructing a SOX9-overexpressing and S100P knockdown colon cancer cell line, we confirmed that knockdown of S100P expression can dramatically decrease SOX9-mediated migration and invasion abilities." (PMID 26009899, 2015). "To explore the expression patterns of SOX9 and S100P in colon cancer, we measured the expression levels of SOX9 and S100P in colon cancer tissues by Q-PCR and Western blot analyses." (PMID 26009899, 2015). "More importantly, S100P plays a pivotal role in SOX9-induced metastasis and invasion of colon cancer." (PMID 26009899, 2015). "Knockdown of S100P in SOX9-overexpressing colon cancer cells dramatically suppressed metastasis and invasion both in vitro and in mice." (PMID 26009899, 2015). "To explore the biological function of SOX9 in colon cancer, we knocked down SOX9 expression in HCT116 cells via lentiviral-mediated transfection." (PMID 26009899, 2015).
colon carcinoma (continued). "We then utilized the lentivirus expressing S100P-specific siRNA to knockdown S100P expression in HCT116-SOX9(+) cells, thus establishing a SOX9-overexpressing and S100P knockdown colon cancer cell line (HCT116-SOX9(+)/S100P(−))." (PMID 26009899, 2015). "A relationship between SOX9 and colon cancer growth and progression as well as colonic epithelial stem cell differentiation has also been reported." (PMID 26009899, 2015). "We also detected SOX9 and S100P expression in a tissue microarray with 90 colon cancer cases to provide their clinical relevance." (PMID 26009899, 2015). "More importantly, S100P was found to be critical for SOX9-mediated metastasis and invasion in colon cancer." (PMID 26009899, 2015). "After calculating the regression coefficient between the expression scores of SOX9 and S100P, we found that there was a significant linear regression between SOX9 and S100P (R2 = 0.782, P < 0.001) in primary colon cancer." (PMID 26009899, 2015). "Among many candidate genes we screened, S100P expression was selectively up-regulated by SOX9 in both colon cancer cell lines and human colon cancer samples." (PMID 26009899, 2015). "SOX9, as a transcription factor of S100P, up-regulates the transcription activity of S100P and promotes metastasis, invasion and poor survival of colon cancer by regulating S100P expression." (PMID 26009899, 2015). "Other SOX factors, such as SOX4 and SOX9, have been reported as tumour-suppressive proteins in bladder, breast, prostate and colon carcinomas." (PMID 18268498, 2008). "It has been reported that other SOX family members, such as SOX4 and SOX9, induce apoptosis in bladder, prostate and colon carcinomas, being consistent with our finding." (PMID 18268498, 2008). "Moreover, biallelic inactivation of Sox9 in an independent mouse colon tumor model (AKP mice) significantly increased the burden of tumors that were high tumor grade, invasive, and metastatic." (PMID 40179020, 2025). "EMT induction in colon tumors with combined Apc and Sox9 inactivation." (PMID 40179020, 2025). "Additionally, claudin gene regulation differs by tissue: CLDN7 is repressed by the transcription factor Sox9 in colon cancer cells, but in ovarian cancer CLDN7 can be silenced by DNA hypermethylation or post-translational phosphorylation." (PMID 40687428, 2025). "Bi-allelic inactivation of the Apc gene induces Sox9 expression in colon cancer." (PMID 38659853, 2024). "Consequently, RIP140 and SOX9 exert opposite effects on Paneth cell differentiation and colon cancer cell proliferation." (PMID 34206767, 2021). "Additionally, many other driver genes are frequently mutated in colon cancer, such as ARID1A, SOX9, FAM123B, BCL9L, RBM10, CTCF, and KLF5." (PMID 34912802, 2021). "SOX9 is also an important player in colon cancer development and progression." (PMID 34206767, 2021). "We also found Sox9 overexpression in chemically induced colon tumors and in Apc and Ctnnb1 mutants." (PMID 27811361, 2016). "There was a strong correlation between SOX9 and S100P expression in colon carcinomas." (PMID 26009899, 2015). "Overexpression of SOX9 (P = 0.038) and S100P (P < 0.001) mRNA was observed in colon cancer." (PMID 26009899, 2015). "In conclusion, we demonstrated that SOX9 and S100P are both overexpressed in colon cancer." (PMID 26009899, 2015). "Knockdown of SOX9 expression down-regulated S100P expression, resulting in reduced invasiveness and metastasis of colon cancer cells by inhibiting the activation of receptor for advanced glycation end products (RAGE)/ERK signaling and epithelial-mesenchymal transition (EMT)." (PMID 26009899, 2015). "Furthermore, knockdown of SOX9 expression reduces the invasiveness and metastasis of colon cancer cells." (PMID 26384302, 2015). "Because SOX9 promotes cell migration and invasion, we investigated whether S100P mediates the effect of SOX9 on cell migration and invasion in colon cancer cells." (PMID 26009899, 2015).